ACE (angiotensin I converting enzyme)
Diseases named in the same sentence as ACE in open-access papers (continued):
Sharing a sentence is not in itself a finding about the gene and the disease.
tumor (continued). "ACE inhibitors have been shown to reduce tumor angiogenesis, likely mediated through vascular endothelial growth factor (VEGF)." (PMID 33513805, 2021). "We demonstrated expression of angiotensinogen by CSCs within the TNs, PRR, and AT2R by the CSCs within the TNs and the PTS, in addition to ACE on the endothelium of tumor microvessels in mHNcSCC." (PMID 33513805, 2021). "Membranous expression of ACE (brown) was present on the endothelium of the tumor microvessels within the PTS in all samples." (PMID 33513805, 2021). "This study suggested that if lung microcapillaries are being lost in the tumor, then circulating ACE activities will decline." (PMID 34359878, 2021). "This also appeared to be the case for ACE, which was rarely seen except on the endothelium of blood vessels within the NC tissues, and occasionally on the luminal membranes of CA tumor epithelial cells where it was weaker in HGCA than LGCA." (PMID 34428252, 2021). "Severe focal infiltration of lymphocytes in the mesentery in tumour-bearing mice was also shown, and ACE showed a significant improvement after administration, especially in the mid-dose group (red arrows)." (PMID 34531745, 2021). "In the discussion of the Asian data the frequency of cough of > 50% in Chinese patients taking ACE inhibitors, leading to a higher rate of tumor detection, should be kept in mind." (PMID 33231730, 2021). "The bioactive compounds in these FSF exhibit ACE inhibitory, antioxidant, anti-tumor, anti-diabetic, antimicrobial, anti-hypertensive, anti-allergic, and immunoregulatory properties." (PMID 34305497, 2021). "After ACE intervention, the alteration was reversed siginificantly compared with those in the tumour-bearing mice." (PMID 34531745, 2021). "Marine-derived peptides have previously been found to possess anti-oxidant, anti-tumor, anti-hypertensive, angiotensin-converting-enzyme (ACE) inhibitory, immunomodulatory, antidiabetic, antimicrobial, anticoagulant, and anti-inflammatory potential." (PMID 34072134, 2021). "Tumour growth was also significantly inhibited by ACE administration (p < 0.05), and the medium dose showed a better tumour suppression rate than the high and low doses, with a rate of 43.43%." (PMID 34531745, 2021). "Immunofluorescence staining of two HNmMM tissue samples demonstrated expression of PRR and AT2R by the SOX2+ CSCs within the TNs and the OCT4+ CSCs within the PTS, with ACE localized to the endothelium of the tumor microvessels within the PTS." (PMID 33147716, 2020). "Recent studies with mouse models of bacterial infection and tumor suggest that ACE plays an important role in the immune responses of myeloid cells." (PMID 32508938, 2020). "Cytoplasmic expression of ACE (green) was demonstrated on the endothelium of the tumor microvessels which showed nuclear staining of ERG (red)." (PMID 33147716, 2020). "In both tumor and infection studies with transgenic mice overexpressing only an active C-domain or an active N-domain, we found that the C-domain of ACE is important for increasing the immune responses of myeloid cells." (PMID 32508938, 2020). "In conclusion, NEP and/or ACE inhibition represents a powerful tool to improve tumor targeting and the overall pharmacokinetics of NT-based radioligands, and warrants further validation in the field of NTS1R-targeted tumor imaging and therapy." (PMID 32526874, 2020). "Consistent with anti-tumor response, the C-domain of ACE predominately enhanced ATP production in these cells." (PMID 32508938, 2020). "Multiple in vitro and in vivo studies have demonstrated a reduction in tumor growth, angiogenesis, and metastasis with administration of various ACE inhibitors." (PMID 33147716, 2020). "Shen and colleagues demonstrated that ACE overexpression reduced the number of blood and splenic myeloid-derived suppressor cells, in a spontaneous tumor model and in a model of chronic inflammation." (PMID 32503281, 2020).
tumor (continued). "In contrast, ACE overexpression in myeloid cells strongly induced bacterial and tumor resistance in mice." (PMID 32508938, 2020). "The conformational fingerprint of ACE from tumor lung tissues differed from normal lung (6/17 mAbs) and reflected primarily higher ACE sialylation." (PMID 31877149, 2019). "This novel finding offers insights into the biology of PG with the potential of using RAS modulators such as β-blockers and ACE-inhibitors, for this common and often troublesome tumor." (PMID 31024924, 2019). "The data show that ACE expression as well as local conformation of ACE is altered by tumor formation." (PMID 31877149, 2019). "Blockade of ACE with captopril increased Kupffer cells infiltration in the tumor-bearing liver during an early stage of tumor progression in CRC liver metastasis." (PMID 30464806, 2018). "Neutral endopeptidase (NEP/CD10), Angiotensin-converting enzyme-2 (ACE2), and aminopeptidase A (APA) were expressed in tumor cells whilst Angiotensin-converting enzyme (ACE) was expressed in the endothelial cells of intratumor blood vessels." (PMID 28809959, 2017). "The tumor-promoting actions of the ACE/AngII/AT1R axis, the main target of classical RASi, have been reviewed elsewhere." (PMID 28978752, 2017). "The novel finding of the expression pattern of PRR, ATIIR1, ATIIR2, and ACE on CSC subpopulations within MDBMSCC provides insights into the biology of this aggressive tumor." (PMID 27730124, 2016). "The ACE 10/10 mice were also tested in a tumor metastasis model where the mice were injected intravenously with B16 tumor cells." (PMID 27018193, 2016). "ATIIR1 and ATIIR2 were localized to the CSC subpopulations within the tumor nests and the peri-tumoral stroma, while ACE was localized to the endothelium of the microvessels within the peri-tumoral stroma." (PMID 27730124, 2016). "This provides potential bypass mechanisms for IH to produce ATII that potentially promotes tumor growth, despite β-blockade or ACE inhibition." (PMID 26137466, 2015). "It provides understanding of the potential multiple pathways contributing to the ultimate levels of the vasoactive peptide, ATII, and highlights the complexity of β-blockade or ACE inhibition in the treatment of this tumor." (PMID 26137466, 2015). "Some studies have shown that ACE inhibitors can significantly inhibit tumor growth and angiogenesis in some malignancies, and suppress VEGF." (PMID 24902660, 2014). "Several studies have shown that ACE (as also known as kininase II) inhibition resulted in anti-tumor effects." (PMID 23691222, 2013). "In immunochemistry, tumor cells are positive for chromogranine A, synaptophysine, ACE and calcitonine." (PMID 23445571, 2013). "While the role of kinin receptors in tumorigenesis is still poorly understood, it has been shown that angiotensin-I converting enzyme (ACE) inhibitors – a widely used family of anti-hypertensive drugs – have anti-tumor properties." (PMID 23691222, 2013). "These same cells, however, remained sensitive to ACE inhibition, suggesting significant differences in the molecular mechanisms by which these agents inhibit tumour growth." (PMID 21703011, 2011). "Tumor induction led to an initial increase in AT1R and ACE expression while captopril treatment significantly increased ACE expression in the final stages of tumor growth." (PMID 20380732, 2010). "A significant increase in ACE mRNA expression was observed at day 5 in the tumor-bearing liver compared to sham livers (P = 0.0412), indicating an effect of tumor induction." (PMID 20380732, 2010). "In the normal liver adjacent to CRC metastases, ACE localized to the hepatic endothelial cells of liver veins and some sinusoidal endothelial cells in both sham operated animals and in tumor-bearing control and captopril treated animals." (PMID 20380732, 2010).
tumor (continued). "Perindopril, another ACE inhibitor has also been shown to be a potent inhibitor of tumour development and angiogenesis through suppression of the VEGF and the endothelial cell tubule formation." (PMID 15813980, 2004). "Bradykinin is one of these substrates and is involved in tissue injury and inflammation, as well as potentially influencing the tumour microenvironment, so increased levels, due to inhibition of ACE, may therefore play a role in tumorigenesis." (PMID 41085561, 2026). "Tumor markers including ACE, CA 19 - 9, and CA 72 - 4 were elevated." (PMID 41627653, 2026). "Captopril, a sulfhydryl-containing dipeptide analog that acts as a potent Angiotensin-Converting Enzyme (ACE) inhibitor that may impact tumor vasculature and immune modulation, is titrated to 50 mg twice daily." (PMID 41304874, 2025). "Similarly, ACE-Is and ARBs have been investigated for their ability to modulate the tumor microenvironment." (PMID 41303679, 2025). "There were no significant abnormal results in the examination of tumor-related indicators such as tumor serum markers, serum/urine protein electrophoresis, serum/urine immunofixation electrophoresis, angiotensin-converting enzyme (ACE), and the vascular endothelial growth factor (VEGF)." (PMID 40917352, 2025). "Inhibition of ACE could lead to the accumulation of bradykinin and substance P, which potentially mediates tumor growth and proliferation 68,80." (PMID 40535814, 2025). "The rNETs-M group showed higher Chao1 and ACE indices than the rNETs-nM group, indicating increased gut microbiota diversity in patients with liver metastasis, which may be related to tumor metastasis to the liver." (PMID 39895797, 2025). "Also, immunosuppression roles have been proposed for ACE in the tumor microenvironment, which provide a potential benefit of ACE inhibition in the development of neoplasm." (PMID 39518949, 2024). "Genes such as MARCO, FN1, ACE, and CD163L1 are likely associated with the immunoregulatory functions of M2 macrophages, which typically promote tissue repair, anti-inflammatory responses, and support tumor growth." (PMID 39697346, 2024). "Some studies have also suggested that abalone peptides have several potential bioactivities such as anti-tumor effects, immune function improvement, anti-microbial, anti-thrombotic, anti-coagulant, and angiotensin-I-converting enzyme (ACE-1) inhibitory activities." (PMID 36834568, 2023). "Furthermore, the Tle12 substitution impaired cell internalization and final tumor uptake of [99mTc]Tc-DT6 during NEP inhibition when compared with the [99mTc]Tc-DT1 reference during double ACE/NEP inhibition." (PMID 37631306, 2023). "Studies looking at mice with independently knocked out N- and C-domains of ACE in myeloid cells revealed that this tumor resistance could be attributed to the ACE C-domain, which seemed to induce macrophages to assume an M1 phenotype." (PMID 36969603, 2023). "ACE synthesizes angiotensin II and stimulates tumor cell growth through AT1R." (PMID 37743493, 2023). "Moreover, ACE and the activation of angiotensin II type 1 receptor (AT1R), critical factors in RAAS, have been associated with tumor growth by stimulating cell proliferation and neovascularization." (PMID 35477724, 2022). "ACE is expressed in rat granulosa cells and is an important regulator of tumor development." (PMID 35565312, 2022). "In addition, substance P is elevated in ACE inhibitor users, which can promote tumor proliferation, migration, and angiogenesis." (PMID 35113855, 2022). "In addition, ACE and its major enzymatic product, Ang II, are recognized as critical determinants of angiogenesis, inflammation, tumor progression, and hematopoiesis." (PMID 36213442, 2022). "Along with ACE inhibition leading to an accumulation of bradykinin and substance P, both potential inducers of tumor proliferation, ACE inhibition can also lead to an increase in Ac-SDKP, an endogenous antifibrotic peptide that is capable of inducing angiogenesis." (PMID 35113855, 2022).
tumor (continued). "ACE (angiotensin converting enzyme) inhibitors have been a chief line of therapy to treat the condition, but these drugs lead to side effects such as hypotension, elevated levels of potassium, impaired renal function, coughing and skin rashes." (PMID 36364899, 2022). "The localization of ACE to the endothelium of the tumor microvessels suggests a role in vasculogenesis, which may reflect ‘vascular mimicry’ and ACE has been identified as a critical regulator of hemangioblast differentiation." (PMID 33513805, 2021). "The results showed that ACE treatment could significantly reduce expressions of Cyclin D1 and C-myc of tumour tissues both in protein and mRNA level." (PMID 34531745, 2021). "ACE was expressed on the endothelium of the tumor microvessels within the PTS." (PMID 33513805, 2021). "The decrease in serum ACE levels might reflect an increased tumor burden as malignant cells destroy these pulmonary epithelial cells." (PMID 33231730, 2021). "The involvement of ACE activity in tumors may be tumor specific or limited to specific ethnic groups." (PMID 34285715, 2021). "ACE is localized to the endothelium of the tumor microvessels within the PTS." (PMID 33147716, 2020). "Furthermore, macrophages from mice with myeloid ACE overexpression were more pro-inflammatory, exhibiting enhanced tumor-killing activity compared to their wild-type mice counterparts." (PMID 32503281, 2020). "ACE was present on the endothelium of the tumor microvessels, mainly located within the PTS." (PMID 33147716, 2020). "They found that ACE overexpression in macrophages increased tumor resistance in mice." (PMID 32508938, 2020). "Thus, this study shows that the overexpression of ACE C-domain by macrophages is a strong mechanism to increase resistance to tumor." (PMID 32508938, 2020). "ACE was localized to the endothelium of the tumor microvessels within the PTS." (PMID 33147716, 2020). "Angiotensin-converting-enzyme (ACE) inhibitors through renin–angiotensin system inhibition may reduce tumor progression and potentially affect SI-NEN-related MF." (PMID 32521677, 2020). "The role of ACE in angiogenesis may explain why it is localized to the endothelium of the tumor microvessels, as demonstrated in this study." (PMID 33147716, 2020). "The substitution of highly specialized prostate epithelial cells by tumor cells results in dramatic decrease in ACE activity in prostate tissues, therefore ACE phenotyping of prostate biopsies may have clinical (diagnostic) significance." (PMID 31695843, 2019). "It is believed that ACE activity may be related to tumor growth and ACE inhibitors as well as angiotensin receptor blockers, thereby contributing to the suppression of tumor growth." (PMID 31554351, 2019). "Local conformation of ACE is significantly altered in tumor lung tissues and may be detected by conformational fingerprinting of human ACE." (PMID 31877149, 2019). "Additionally, both ACE inhibitors or angiotensin receptor blockers effectively suppress NSCLC cell proliferation as well as metastases to prevent further tumor formation." (PMID 31133857, 2019). "ACE inhibitors and ARBs suppress tumor growth, angiogenesis and invasiveness." (PMID 27646033, 2016). "Therefore, we were first interested to study the potential involvement of ACE on the tumor uptake of [111In-DOTA]MG11." (PMID 26882895, 2016). "When B16 tumor cells constitutively expressing ovalbumin were used, tetramer analysis of T-cell receptors showed that ACE 10/10 mice have more circulating tumor-specific CD8+ T cells with specificity for the ovalbumin epitope SIINFEKL and the B16 TRP-2 epitope (SVYDFFVWL) than WT mice." (PMID 27018193, 2016). "In this context, it seems discordant that ACE blockade could play its anti-tumor role by increasing the activity of a pro-tumor system, i.e., the kallikrein-kinin system." (PMID 23691222, 2013).
tumor (continued). "Therefore, most of the anti-tumor properties of ACE inhibitors have been eventually attributed to a decreased AT1 receptor activation." (PMID 23691222, 2013). "ACE inhibition with captopril was found to retain its anti-tumour activity." (PMID 21703011, 2011). "In these studies, ACE inhibitors showed a decrease in tumor growth and VEGF levels." (PMID 20431722, 2010). "First the drop in blood pressure induced by captopril-mediated ACE inhibition may account for some of its anti-tumour activity." (PMID 16753063, 2006). "ACE mRNA was also lower in tumour tissue compared with normal tissue." (PMID 16755291, 2006). "Other possible mechanisms of action of ACE inhibitors such as enalapril, captopril, and perindopril against tumor cells may involve the inhibition of matrix metalloprotease activity, reduction in vascular endothelial growth factor expression, and interference with the RAAS system." (PMID 36831338, 2023). "However, it was shown that despite ACE inhibition, the pro-tumor pathway via AT1R could still be activated by an ACE-independent pathway by chymase, which is an enzyme that is activated under conditions of local inflammation." (PMID 35879682, 2022). "Thus, it seems unlikely this SNP might impact the ACE/AngII/ATR1 axis, which has been associated with tumour cell growth and angiogenesis, partially justifying the absence of clinical impact in NSCLC patients with advanced stage disease." (PMID 33353148, 2020). "We suggest that these conformational changes in ACE may be related to 1) greater levels of sialylation in the lung tumor tissue or, alternatively, 2) expression of proteins in tumor tissue that may be novel ACE effectors–like ACE effector found in normal spleen tissue." (PMID 31877149, 2019). "A study also reported that the blockade of ACE or the AT1 receptor may reduce tumor growth." (PMID 28533754, 2017). "Therefore, our aim was to examine the role of ACE in tumor cell proliferation and migration." (PMID 27992423, 2016). "ACE protein was found in tumour-associated and non-tumoral vessels." (PMID 14997208, 2004). "Quantitative analysis of tumor-infiltrating immune cells (TIICs) and functional assays revealed significant differences in the roles of ACE and HSPB8 between normal lung and LUSC cells, underscoring their importance in tumor biology and epigenetic regulation." (PMID 41490177, 2026). "The ACE/AngII/AT1R pathway is elevated across a wide spectrum of malignancies, linking it to tumor growth and dissemination." (PMID 41301459, 2025). "The primary endpoint will be progression-free survival (PFS), with changes in RAS component expression (ACE, ACE2, AT1R) in plasma and tumor biopsies serving as secondary endpoints." (PMID 41301459, 2025). "The enzymatic hydrolysis of food materials produces smaller peptides with various functional properties, including antibacterial, anti-angiotensin-converting enzyme (ACE), anti-tumor, anti-lipid accumulation, and antioxidant activities." (PMID 39123656, 2024). "Both the mice expressing increased WT ACE (Tg-ACE) and the Tg-NKO mice having an active C domain showed reduced B16 tumor growth (16% and 23% of WT tumor volume) similar to what is seen in ACE 10/10 mice." (PMID 38763333, 2024). "As expected, tumor uptake in mice was markedly improved, highlighting NEP/ACE-resistance as a crucial feature in the performance of NT–radioligands." (PMID 37631306, 2023). "Previous studies in mice, demonstrated that targeted overexpression of ACE in CD115+ myelomonocytic cells (ACE10 models) improved their immune responses to effectively reduce viral and bacterial infection, tumor growth, and atherosclerotic plaque." (PMID 37427403, 2023). "Since the enhanced tumour resistance continues with AT1R inhibition, it follows that this exaggerated macrophage phenotype is Ang II-independent and involves the ACE-mediated hydrolysis of peptides yet to be identified." (PMID 36016727, 2022).